BDNF (brain derived neurotrophic factor)
Diseases named in the same sentence as BDNF in open-access papers (continued):
Sharing a sentence is not in itself a finding about the gene and the disease.
sarcopenia (continued). "The assessment of BDNF, IL-8, sTNFr-1, and sTNFr-2 levels may be an adjuvant tool in diagnosis and severity classification of Sarcopenia in older Brazilian women." (PMID 37365209, 2023). "Interestingly, the most significant differences were observed between sarcopenic groups, suggesting the involvement of BDNF in the severity of Sarcopenia." (PMID 37365209, 2023). "On the other hand, aberrant activation of the BDNF-TrkB axis has been described in age-related pathologies such as lung fibrosis, sarcopenia, cancer, and kidney disease; interestingly, all these processes causing age-associated declines and diseases have been linked to cellular senescence." (PMID 36266274, 2022). "It has been suggested that BDNF signaling may play an essential role in regulating neuromuscular function during ageing, which may have implications for the pathogenesis of sarcopenia and SO." (PMID 35011721, 2022). "We hypothesized that chronic treatment with 7,8‐dihydroxyflavone (7,8‐DHF), a small molecule BDNF analog and TrkB agonist, will mitigate age‐related diaphragm neuromuscular transmission failure and sarcopenia in old mice." (PMID 28082429, 2017). "BDNF participates in the neuronal differentiation and survival, but in the skeletal muscle it is involved in the maintenance of motor units and reduces the denervation-induced atrophy seen in sarcopenia." (PMID 27832209, 2016). "Therefore, we speculate that CI leads to a decrease in BDNF levels in brain tissue, which in turn reduces the amount of BDNF entering the bloodstream, subsequently affecting muscle function and increasing the incidence of sarcopenia." (PMID 40677895, 2025). "Additionally, although the irisin/BDNF ratio appears to be a promising indicator of sarcopenia, its interpretation remains uncertain—it is unclear whether it represents a reliable biomarker or merely reflects a state of physiological imbalance." (PMID 41154577, 2025). "Interestingly, a link between lower levels of BDNF and sarcopenia is evident in the literature." (PMID 38790190, 2024). "Therefore, deterioration of skeletal muscle mass in sarcopenia, along with limited physical activity or a sedentary lifestyle in the elderly, may contribute to decreased levels of BDNF." (PMID 37577356, 2023). "Finally, reduced physical exercise, generated by sarcopenia, may decrease the level of the brain-derived neurotrophic factor which is related to learning and memory." (PMID 36158553, 2022). "Therefore, BDNF may serve as a potential surrogate marker of sarcopenia and muscle exercise." (PMID 40400914, 2025). "Both BDNF and GDNF were shown to potentially play a role in the diagnosis of sarcopenia in chronic obstructive pulmonary disease (COPD) and Parkinson’s disease (PD) patients." (PMID 38398421, 2024). "Our primary finding was the longitudinal correlation of circulating CAF22, BDNF, and GDNF with sarcopenia indexes during the disease course of COPD." (PMID 34575696, 2021). "The current study aims to address this gap by evaluating circulating BDNF, GDNF, and CAF22 levels as potential biomarkers of sarcopenia in COPD." (PMID 34575696, 2021). "The main strength of the current study was that it simultaneously considered the relationship between several biomarkers, including myostatin, follistatin, oxytocin, BDNF, DHEA, T2 and E2, and osteoporosis and/or sarcopenia in the same study population." (PMID 34641817, 2021). "We applied logistic regression coefficients to the circulating CAF22, BDNF, and GDNF levels to generate predicted probabilities of individual biomarkers for clinical sarcopenia." (PMID 34575696, 2021). "Additionally, plasma levels of myokines like BDNF and soluble TNF receptors correlate with functional and respiratory performance, offering further prognostic insights when combined with sarcopenia index." (PMID 41450343, 2025).
sarcopenia (continued). "Although interventional studies with physical exercise in animal models show that activity and immobilization alter serum and muscle BDNF levels, there are no direct randomized data from human cohorts on BDNF modulation in sarcopenia." (PMID 41303670, 2025). "Physical exercise, particularly resistance-based protocols, remains the most effective non-pharmacological strategy to upregulate BDNF and mitigate sarcopenia progression." (PMID 41441428, 2025). "Our results suggested that BDNF, JAK2, RhoC, Myh6, Stat5a, Tnnc1, and other genes may mediate the beneficial effects of exercise on sarcopenia through these pathways." (PMID 39309455, 2024). "For series 1, the group agreed on 4 biochemical markers that should be assessed in Phase II or Phase III trials (i.e., Myostatin-Follistatin, Brain Derived Neurotrophic Factor, N-terminal Type III Procollagen and Serum Creatinine to Serum Cystatin C Ratio – or the Sarcopenia Index)." (PMID 36633611, 2023). "Altogether, measurements of plasma CAF22, BDNF, and GDNF may be helpful for the accurate diagnosis of sarcopenia and functional capacity in COPD during PR." (PMID 34575696, 2021). "We evaluated the circulating biomarkers of NMJ degradation, including c-terminal agrin fragment -22 (CAF22), brain-derived neurotrophic factor (BDNF), and glial cell line-derived neurotrophic factor (GDNF) as predictors of sarcopenia in COPD during pulmonary rehabilitation (PR)." (PMID 34575696, 2021). "Thus, the reduced upregulation of BDNF and GDNF in the elderly can potentially contribute to sarcopenia in COPD." (PMID 34575696, 2021). "Physical inactivity resulting from sarcopenia may also decrease the expression of insulin-like growth factor-1 (IGF-1) and brain-derived neurotrophic factor (BDNF) which are known to be modulating factors for brain neuroplasticity." (PMID 32076075, 2020). "Biomarkers such as C-terminal agrin fragment-22 (CAF22), brain-derived neurotrophic factor (BDNF), and glial cell line-derived neurotrophic factor (GDNF) have been identified as predictors of sarcopenia and may guide pharmacologic strategies during pulmonary rehabilitation." (PMID 41450343, 2025). "Transcriptomic analysis identified BDNF, JAK2, RhoC, Myh6, Stat5a, and Tnnc1 as core target genes that may mediate the effects of different exercise intervention stimuli through the JAK-STAT, cGMP-PKG, and Rap1 pathways to improve the skeletal muscle phenotype of sarcopenia." (PMID 39309455, 2024). "Collectively, these results indicate that enhancing BDNF/TrkB signaling with 7,8‐DHF delivered chronically starting at an early old age (18 months of age) is not effective to mitigate sarcopenia in the diaphragm muscle." (PMID 28082429, 2017).
fibromyalgia (49 papers, 2013 to 2026). A chronic disorder of unknown etiology characterized by pain, stiffness, and tenderness in the muscles of neck, shoulders, back, hips, arms, and legs. "For instance, higher serum BDNF levels were associated with lower pressure pain thresholds in patients with fibromyalgia." (PMID 38254671, 2024). "Research on genetic factors, including genetic variations or single nucleotide polymorphisms, especially related to BDNF in fibromyalgia is very limited." (PMID 32859253, 2020). "Clinical studies have found higher levels of BDNF in the blood and cerebrospinal fluid in patients with chronic pain, and in fibromyalgia has been associated with a lower pain threshold." (PMID 27445748, 2016). "Fibromyalgia has been reported to be associated with the up-regulation of BDNF in the cerebrospinal fluid, and the extent of this up-regulation was correlated with the duration of chronic pain." (PMID 25383981, 2014). "In addition, certain BDNF polymorphisms have an effect on specific aspects of brain function such as default mode network connectivity, which is currently considered to be central in the pathogenesis of fibromyalgia." (PMID 38254671, 2024). "Given that the extant literature broadly implicates BDNF as a biomarker in fibromyalgia, and further hypothesises NGF to be implicated in the peripheral pathophysiology of fibromyalgia, our null findings will adjust how clear the current study consensus appears." (PMID 31541132, 2019). "Altogether, our study identified the BDNF/IL-33 regulatory pathway as a molecular correlate of fibromyalgia, and the use of US-exposed young C57BL/6 mice as a potential model that recapitulates this syndrome." (PMID 42123637, 2026). "Unfortunately, given the small sample size of participants with CP and migraine (n = 28) or fibromyalgia (n = 31), we were unable to thoroughly evaluate the impact of CP on BDNF in the context of these conditions." (PMID 40222813, 2025). "Elevated levels of BDNF have been consistently detected in the cerebrospinal fluid (CSF), serum, and peripheral blood mononuclear cells (PBMCs) of patients suffering from fibromyalgia, chronic low-back pain, migraine, and other persistent pain conditions." (PMID 40940732, 2025). "In contrast, the same researchers reported in 2021 that WBV treatment for 6 weeks can increase the expression of BDNF in women with fibromyalgia." (PMID 39144715, 2024). "We previously reported that patients with chronic fatigue syndrome and comorbid fibromyalgia exhibited lower DNA methylation levels in the BDNF gene compared to healthy individuals, correlating with increased serum BDNF levels and hyperalgesia." (PMID 39125894, 2024). "Increased plasma levels of BDNF have also been reported in other chronic pain conditions, e.g., primary headaches and fibromyalgia." (PMID 35628904, 2022). "Here we show that fibromyalgia patients carrying the Val/Met BDNF genotype presented an increased ΔFC across MC and PFC in response to acute pain associated with differences in acute pain perception and fibromyalgia symptoms." (PMID 36336706, 2022). "For instance, in patients with OA, the BDNF level is lower compared to that in HSs, whereas it is higher in patients with fibromyalgia." (PMID 33915758, 2021). "Based on these data, Laske and collaborators were the first to examine serum BDNF concentrations in patients with fibromyalgia and found that their levels were dramatically increased compared to healthy controls." (PMID 33918736, 2021). "Some studies report BDNF in different chronic pain patients, including fibromyalgia and osteoarthritis." (PMID 33915758, 2021). "Two separate groups observed substantially higher levels of BDNF in the plasma and cerebral spinal fluid of fibromyalgia patients than in controls, suggesting the involvement of BDNF in fibromyalgia pathophysiology." (PMID 33918736, 2021). "The studies that showed an agreement with an increase in the BDNF level in fibromyalgia only recruited female patients." (PMID 33915758, 2021).
fibromyalgia (continued). "Brain-derived neurotrophic factor (BDNF) has been shown to play a role in patients with fibromyalgia syndrome, particularly in mediating manifestations of pain and mood-related symptoms." (PMID 32859253, 2020). "For the present study we investigated plasma levels of NGF, as well as BDNF as a replication attempt in a large sample of fibromyalgia patients." (PMID 31541132, 2019). "Higher serum BDNF levels have also been reported in the setting of other chronic pain conditions, such as fibromyalgia, chronic musculoskeletal pain, migraine, and chronic tension-type headache." (PMID 31632254, 2019). "The present study findings contradict those from previous studies measures BDNF in blood of fibromyalgia patients, and this finding should be explored further." (PMID 31541132, 2019). "This is the first study to show that peripheral NGF is unperturbed in fibromyalgia patients, and further sheds doubt upon previous findings that plasma BDNF is increased in fibromyalgia." (PMID 31541132, 2019). "In human, increased serum BDNF has been consistently reported in chronic pain conditions such as fibromyalgia, chronic musculoskeletal pain, chronic tension-type headache and myofascial pain syndrome." (PMID 31632254, 2019). "Several lines of evidence imply that brain-derived neurotrophic factor (BDNF) is involved in the pathophysiology of fibromyalgia (FM); in this regard, patients with FM have altered blood and cerebrospinal fluid levels of BDNF." (PMID 30285822, 2018). "This statement is also supported indirectly by clinical findings, where the serum BDNF was correlated inversely with the pressure pain threshold in fibromyalgia." (PMID 27445748, 2016). "Fibromyalgia (FM) is conceptualized as a central sensitization (CS) condition, that presents high serum brain-derived neurotrophic factor (BDNF) and neuroglia activation." (PMID 25005881, 2014). "A role for BDNF protein in chronic pain conditions such as irritable bowel syndrome and fibromyalgia has been suggested." (PMID 25383981, 2014). "For example, increased body mass index mediated the association of a common functional SNP in the gene of brain-derived neurotrophic factor (BDNF Val66Met) with fibromyalgia syndrome." (PMID 24278778, 2013). "In addition, DNA hypomethylation (exon 9) of brain-derived neurotrophic factor (BDNF) was found in blood cells of patients with chronic fatigue syndrome and comorbid fibromyalgia." (PMID 41439979, 2025). "BDNF levels are also increased in fibromyalgia and other primary chronic pain disorders." (PMID 39909798, 2025). "The relationship between CP and circulating BDNF levels has been investigated in approximately thirty human studies, with most focusing on fibromyalgia." (PMID 40222813, 2025). "Other investigations have disclosed an association between BDNF polymorphism and fibromyalgia, and a systematic review and meta-analysis study demonstrated that the circulating BDNF levels are significantly higher in patients suffering from fibromyalgia than in controls." (PMID 38785946, 2024). "The Val66Met polymorphism may have a direct effect on gene methylation, and the resulting expression and data show that individuals with chronic fatigue syndrome and fibromyalgia have higher amounts of BDNF in their bloodstream." (PMID 38785946, 2024). "In another study, plasma samples were analyzed after a 15-week progressive resistance exercise to show that the levels of NGF are unchanged while those of BDNF increase, suggesting that BDNF may affect nociception/pain in fibromyalgia." (PMID 38785946, 2024). "Several clinical trials were devoted to the study of BDNF levels in fibromyalgia because people diagnosed with this condition exhibit elevated levels of serum BDNF compared to healthy persons, suggesting a significant involvement of BDNF in the pathophysiology of the disorder." (PMID 38785946, 2024).
fibromyalgia (continued). "However, it remains to be explored whether BDNF Val66Met polymorphism substantially modulates the process of central sensitization and whether a specific genotype(s) renders PDMs more vulnerable to the development of irritable bowel syndrome and fibromyalgia later in life." (PMID 25383981, 2014). "Finally, one review found that the difference in levels of IL-6, IL-8, TNF-α, and brain-derived neurotrophic factor (BDNF) may have the potential to be used for stratification of patients with fibromyalgia into subgroups for future targeted therapies." (PMID 41598488, 2026). "Other proposed biomarkers in fibromyalgia, such as serum brain-derived neurotrophic factor (BDNF) levels or cerebrospinal fluid cytokine profiles, may offer greater pathophysiological specificity but require specialized assays or invasive procedures, making them impractical for routine clinical use." (PMID 41517404, 2025). "Indeed, BDNF levels in patients treated with MC (median value 1672.6 pg/mL) were higher than BDNF levels in both healthy subjects (167.1 ± 171.2 pg/mL) and in patients with fibromyalgia (113.8 ± 149.6 pg/mL), as reported in the literature." (PMID 40407530, 2025). "In contrast, a study of people with fibromyalgia found that both plasma and serum levels of BDNF were higher in patients than in healthy controls, leading to the hypothesis that BDNF is higher in patients with fibromyalgia because it participates in many compensatory modulatory mechanisms of pain." (PMID 38396487, 2024). "Specifically, the ABCT has shown its efficacy and applicability for the treatment of fibromyalgia showing improvements on psychological outcomes such as functional status and biological outcomes such as reduced brain-derived neurotrophic factor (BDNF) and inflammatory biomarkers." (PMID 36574408, 2022). "The ability of ketamine to modulate NMDAR, glutaminergic signaling, BDNF, descending inhibition, and inflammation and thereby result in a reduction of central sensitization may provide a comprehensive approach for the management of patients with fibromyalgia." (PMID 34984054, 2021). "In addition, according to previous studies, its effect is likely state-dependent neuroplasticity, since the brain-derived-neurotrophic-factor (BDNF) predicted the impact of tDCS on short-term memory in patients with fibromyalgia and the disability due to pain after hallux valgus surgery." (PMID 31297046, 2019). "On the other hand, in a study on fibromyalgia, attachment-based compassion therapy seemed to reduce serum BDNF and appeared to be correlated to anti-inflammatory effects on patients, leading to speculation that reduction in BDNF could be a mechanism of functional status improvement." (PMID 38785946, 2024). "The upregulation of brain-derived neurotrophic factor mediated by NGF participates in the pathophysiological processes, leading to long-term neuroplastic changes in persistent chronic pains, e.g., fibromyalgia." (PMID 37065490, 2023). "The results showed significant improvements in the ABCT group Fibromyalgia Impact Questionnaire (FIQ) and a decrease in BDNF, CRP, and pro-inflammatory composite compared to the RT group." (PMID 36231406, 2022). "This study aimed to investigate the efficacy of whole-body vibration training (WBVT) on blood brain-derived neurotrophic factor (BDNF) levels and determine the clinical and functional outcomes in patients with fibromyalgia syndrome (FMS)." (PMID 34900203, 2021). "Plasma BDNF and NGF were measured in 89 fibromyalgia patients and 36 pain-free controls, and compared using ANCOVA controlling for potential confounders, as well as Bayesian methods for parameter estimation and model evaluation." (PMID 31541132, 2019). "This cross-sectional study set out to assess and compare brain-derived neurotrophic factor (BDNF) and nerve growth factor (NGF) in plasma samples from fibromyalgia patients and healthy controls." (PMID 31541132, 2019).